MALAT1 (metastasis associated lung adenocarcinoma transcript 1)
Diseases named in the same sentence as MALAT1 in open-access papers (continued):
Sharing a sentence is not in itself a finding about the gene and the disease.
lung diseases (7 papers, 2021 to 2023). "Hypoxia is common in lung diseases and a potent stimulator of the long non-coding RNA Metastasis-Associated Lung Adenocarcinoma Transcript 1 (MALAT1)." (PMID 36105289, 2022). "MALAT1 was one of the first lncRNAs to be associated with human disease, and it plays an important role in lung disease." (PMID 36419933, 2022). "MALAT1 influences the progression of lung disease by regulating a range of disease-associated molecules." (PMID 36419933, 2022). "Altogether, the results support the notion that Malat1 shapes rather detrimentally the altered lung function caused by hypoxia, and may perhaps play a similar role in lung disorders involving hypoxia, such as COPD." (PMID 36105289, 2022). "Through interaction with target proteins such as miRNAs, MALAT1 can alleviate lung disease progression, or at least mitigate it." (PMID 37250901, 2023). "In summary, with these clues, it is worthwhile to start thinking about MALAT1 is a potential biomarker for lung diseases." (PMID 37250901, 2023). "Several drugs have also shown to improve tissue injury through targeting MALAT1 in experimental models of lung diseases." (PMID 37250901, 2023). "Since MALAT1 plays important roles in the pathogenesis of lung diseases, identifying its biomarker potential would help in successful prognosis, diagnosis, and treatment of disease." (PMID 37250901, 2023). "Emerging studies suggest that lncRNA MALAT1 plays a significant role in the pathogenesis of lung diseases." (PMID 37250901, 2023). "Here we discuss the roles and molecular mechanisms of MALAT1 in the pathogenesis of these lung diseases." (PMID 37250901, 2023). "MALAT1 is also involved in various other lung diseases as detailed in earlier sections of this review." (PMID 37250901, 2023). "Here, we summarize the roles and molecular mechanisms, therapeutic and biomarker potential of MALAT1 in lung diseases." (PMID 37250901, 2023). "MALAT1 is an important lncRNA that, when extensively explored, can end our eager search for the much-anticipated breakthroughs in efficient treatments for lung diseases, making MALAT1 a potential therapeutic target for lung disease treatment." (PMID 37250901, 2023). "MALAT1 mediates the regulation of multiple pathophysiological responses and exerts various effects on pulmonary diseases by controlling NF-κB, CD, miR, and cytokines." (PMID 36419933, 2022). "This evidence suggests that MALAT1 is an important entity in lung disease study and management, and it has the potential of being both a reliable biomarker in lung diseases and therapeutic target for lung disease treatment." (PMID 37250901, 2023). "However, to achieve this, additional work has to be done, which relates to addressing some of the limitations indicated in previous studies on MALAT1 and lung disease relationships." (PMID 37250901, 2023). "Although these findings imply that the use of these drugs targeting MALAT1 could be effective in treating various lung diseases, further research is necessary to fully understand their precise mechanisms of action." (PMID 37250901, 2023). "Targeting MALAT1 with RNAi approach, microRNA response elements, and ASOs could be potentially useful for developing MALAT1 targeted therapies in lung diseases." (PMID 37250901, 2023). "MALAT1 is a key long-stranded non-coding RNA that plays a vital role in lung diseases." (PMID 37275887, 2023). "Thus, we hypothesized that MALAT1 could be involved in pulmonary adaptations to hypoxia and, thereby, could impact lung diseases deleteriously or beneficially by shaping the altered lung function caused by hypoxia." (PMID 36105289, 2022). "Through this review, we hope to cast light on the regulatory mechanisms of MALAT1 in ALI and chronic lung disease and provide a promising approach for lung disease treatment." (PMID 36186445, 2022).
lymphoma (7 papers, 2017 to 2025). A malignant (clonal) proliferation of B- lymphocytes or T- lymphocytes which involves the lymph nodes, bone marrow and/or extranodal sites. "According to our results, hsa-miR-150-5p, hsa-miR-335-5p, MALAT1 and NEAT1 were differentially expressed in patients with high grade lymphomas when compared to low grade lymphoma patients, indicating their involvement in the pathogenesis and prognosis of NHL." (PMID 35008626, 2021). "The plasma levels of MALAT1 and NEAT1 were higher in patients with high grade lymphoma compared to low grade lymphoma (p = 0.035 and p = 0.018, respectively)." (PMID 35008626, 2021).
metastasis (7 papers, 2007 to 2024). The spread or migration of cancer cells from one part of the body (where they first appeared) to another. "Another classic oncogenic lncRNA is Metastasis-Associated Lung Adenocarcinoma Transcript 1 (MALAT-1), which was widely expressed in normal human tissues, but was upregulated in six other types of cancer." (PMID 23680400, 2013). "The downregulation of MALAT1 (Metastasis-Associated Lung Adenocarcinoma Transcript 1) could have a similar meaning." (PMID 32714991, 2020). "LncRNA LINC00152, HEGBC, MALAT1 and ROR showed a marked correlation with positive lymph node metastasis (LNM), while lncRNA GCASPC, MEG3, LET and UCA1 had the opposite effect." (PMID 31297033, 2019).
non-alcoholic fatty liver disease (7 papers, 2021 to 2024). "MALAT1 expression has been associated with increased oxidative stress and pro-inflammatory cytokines in diabetic and non-alcoholic fatty liver disease (NAFLD) models." (PMID 36653874, 2023). "In human liver tissues, the up regulation of MALAT1 expression is associated with the progression of nonalcoholic fatty liver disease (NAFLD)." (PMID 36452326, 2022). "In nonalcoholic fatty liver disease, lnc-H19 and lnc-Malat1 jointly mediate the stability of SREBP1c." (PMID 34597331, 2021). "In conclusion, this study revealed that MALAT1 could promote hepatic lipogenesis in nonalcoholic fatty liver disease by modulating miR-206/ARNT axis." (PMID 35769097, 2022). "MALAT1 abundance in liver tissue is closely related to the pathological changes in non-alcoholic fatty liver disease (NAFLD), a clinicopathologic syndrome characterized by diffuse bullae steatosis (abnormal accumulation of lipids in liver tissues) not caused by alcohol or other hepatotoxic factors." (PMID 35145971, 2021).
periodontitis (7 papers, 2020 to 2025). An acute or chronic inflammatory process that affects the tissues that surround and support the teeth. "Notably, metastasis-associated lung adenocarcinoma transcript 1 (MALAT1) is also related to periodontitis progression." (PMID 33604388, 2021). "Notably, in silico analysis of miRNA and mRNA expression profiles has shown the role of MALAT1 in construction of the lncRNA-associated competing endogenous RNA network of periodontitis." (PMID 32346660, 2020). "To confirm these findings, we examined MALAT1, and miR-30b expression in gingival biopsies collected from periodontally healthy and diseased human subjects as well as mice with ligature-induced periodontitis." (PMID 37860007, 2023). "While both MALAT1 and ANRIL are influenced by periodontitis, MALAT1 appears to contribute to neuroprotection, whereas ANRIL has neurodegenerative consequences." (PMID 38249527, 2023). "Whereas the knockdown of MALAT1 is reported to inhibit the progression of chronic periodontitis via miR-769-5p." (PMID 37860007, 2023). "MALAT1 expression is obviously increased in PDLSCs isolated from periodontitis patients, and its overexpression promotes cell proliferation." (PMID 33604388, 2021). "Recently, studies have demonstrated that MALAT1 participates in the development of periodontitis and is upregulated in PDLSCs and inflammatory gingival tissues of CP." (PMID 33604388, 2021). "MALAT1 lncRNA increased in chronic periodontitis modulating expression of pro-inflammatory cytokines via miR-20a and TLR pathway." (PMID 33902683, 2021). "Expression of MALAT1 has been up-regulated in primary human gingival fibroblasts obtained from patients with periodontitis compared with controls." (PMID 32346660, 2020). "In human subjects with periodontal disease and murine model of ligature-induced periodontitis, we observed higher levels of MALAT1, M1Mφ markers and downregulation of miR-30b expression in gingival tissues suggesting a pro-inflammatory function of MALAT1 in vivo." (PMID 37860007, 2023). "We examined MALAT1 and miR-30b profiles and their relationship with macrophage polarization markers in gingival (gum) biopsies collected from periodontally diseased human subjects and mice model of ligature-induced periodontitis." (PMID 37860007, 2023). "Several studies have reported the aberrant expression of lncRNAs including POIR, MALAT1, ANRIL, FGD5-AS1, NEAT1, and NKILA in periodontitis patients compared with healthy subject." (PMID 33902683, 2021). "Although the role of lncRNAs in the pathophysiology of periodontitis has been uncovered, data regarding expression pattern of ANRIL or MALAT1 in gingival tissues or peripheral blood of patients with periodontitis is scarce." (PMID 32346660, 2020). "A previous study performed in patients with periodontitis and healthy subjects revealed that blood MALAT1 expression was not correlated with age41." (PMID 40350526, 2025). "Additional studies have shown that MALAT1 role in the pathogenesis of SLE is exerted through regulation of SIRT1 signaling, a pathway which is probably important in the reactive oxygen species homeostasis in the process of development of periodontitis." (PMID 32346660, 2020).
schizophrenia (7 papers, 2019 to 2025). A major psychotic disorder characterized by abnormalities in the perception or expression of reality. "Using an integrative approach combining bulk transcriptomics, snRNA-seq, and an MK-801 mouse model, we observed reduced OXPHOS in schizophrenia and identified three candidate genes—MALAT1, PPIL3, and ITM2A—associated with this process." (PMID 41199749, 2025). "To probe its molecular basis in schizophrenia, we applied complementary methodologies with multi-level validation, which converged on three genes—MALAT1, PPIL3, and ITM2A—that consistently correlated with OXPHOS activity." (PMID 41199749, 2025). "In schizophrenia, we found that MALAT1 is highly expressed across multiple cell types, including neurons, and negatively correlates with OXPHOS." (PMID 41199749, 2025). "For example, two lncRNAs, GOMAFU and NEAT2/MALAT1, have been known to affect mRNA splicing of genes previously shown to be associated with schizophrenia." (PMID 36005827, 2022). "We selected six lncRNAs namely HOXA-AS2, Linc-ROR, MEG3, SPRY4-IT1, UCA1 and MALAT1 to assess their expression in peripheral blood of patients with schizophrenia and healthy subjects." (PMID 31484957, 2019). "Elevated MALAT1 levels have been detected in the peripheral blood of patients with schizophrenia and correlate positively with disease duration, yet its role in the nervous system remains unclear." (PMID 41199749, 2025). "MIAT, NEAT1, and MALAT1 are coordinately changed in schizophrenia." (PMID 36412908, 2022). "However, to the best of our knowledge, this is the first time that a sexual dimorphism is reported for Malat1 in the CNS, which could be relevant in neurological disorders with a marked gender influence, such as schizophrenia, depression, AD disease, or ALS." (PMID 41465496, 2025). "ROC analysis showed that five genes—MALAT1, PPIL3, ITM2A, MTA2, and GJA1—effectively distinguished schizophrenia from controls (AUC >0.70)." (PMID 41199749, 2025). "While Gomafu, PINT, GAS5, TCONS_l2_00021339, IFNG-AS1, FAS-AS1, PVT1, and TUG1 are among down-regulated lncRNAs in schizophrenia, MEG3, THRIL, HOXA-AS2, Linc-ROR, SPRY4-IT1, UCA1, and MALAT1 have been up-regulated in these patients." (PMID 34220567, 2021). "Based on the acknowledged roles of lncRNAs in neurodevelopment, in the current study, we assessed expression of six lncRNAs namely HOXA-AS2, Linc-ROR, MALAT1, MEG3, SPRY4-IT1 and UCA1 in peripheral blood of 60 patients with schizophrenia and 60 healthy subjects." (PMID 31484957, 2019). "Correlation analysis linked OXPHOS scores positively with PPIL3 and ITM2A, negatively with MALAT1 and GJA1, and not significantly with MTA2, suggesting their role in schizophrenia-related mitochondrial dysfunction." (PMID 41199749, 2025).
chronic obstructive pulmonary disease (6 papers, 2021 to 2024). A chronic and progressive lung disorder characterized by the loss of elasticity of the bronchial tree and the air sacs, destruction of the air sacs wall, thickening of the bronchial wall, and mucous accumulation in the bronchial tree. "As previously proposed, MALAT1 represents a diagnostic target for chronic obstructive pulmonary disease." (PMID 34266379, 2021). "This study aimed to investigate the role of methylation of MALAT1 and miR-146a in the pathogenesis of chronic obstructive pulmonary disease (COPD)." (PMID 34604205, 2021). "In non-TGF-β-treated cells, silencing of the metastasis-associated in lung adenocarcinoma transcript 1 (MALAT1) activates mTORC1, associated with cell senescence in chronic obstructive pulmonary disease (COPD)." (PMID 36230902, 2022).
Cirrhosis (6 papers, 2017 to 2023). A chronic disorder of the liver in which liver tissue becomes scarred and is partially replaced by regenerative nodules and fibrotic tissue resulting in loss of liver function. "Further analysis of the AUC curve confirmed that MALAT1 expression was helpful in the differentiation of patients with cirrhosis, vascular invasion, capsule infiltration, and AFP positivity." (PMID 36685103, 2022). "In subgroup analysis of patients with vascular invasion, cirrhosis, and HBsAg positive or AFP positive, MALAT1 overexpression was significantly associated with shorter PFS and OS." (PMID 36685103, 2022). "Given the presence of elevated MALAT1 levels in HCC, the biological functions of MALAT1 remain largely unclear and require further studies regarding their roles in the progression of chronic liver disease, from cirrhosis to HCC." (PMID 32326098, 2020). "Interestingly, plasma MALAT1 levels in HCC patients with HBV infection were lower than those with HCV, and in those HCC patients with liver damage or cirrhosis, MALAT1 levels were substantially higher." (PMID 30159431, 2017). "Another four studies revealed that the serum TGFB2/TGFB2-OT1, lnc-SPARCL1-1:2, lncRNA RABGAP1L-DT-206, MALAT1, Neat1, and HULC expression were significantly higher in patients with advanced fibrosis/cirrhosis (F = 3–4) than in those without it (F = 0–2)." (PMID 36979495, 2023).
Cognitive impairment (6 papers, 2014 to 2025). Abnormal cognition is characterized by deficits in thinking, reasoning, or remembering. "Of note, a previous study reported that Malat1 is increased in the hippocampus of alcoholics, a condition clearly linked to cognitive impairment." (PMID 25431548, 2014). "This association suggests that elevated MALAT1 may impair mitochondrial energy production in neurons, thereby contributing to synaptic dysfunction and cognitive deficits." (PMID 41199749, 2025). "Previous studies have shown that MALAT1 is upregulated in the hippocampus of diabetic rats, resulting in cognitive impairment." (PMID 37740187, 2023). "The MALAT1/miR-382-3p/BDNF signaling pathway may play a key regulatory role in cognitive impairment in T2DM." (PMID 37740187, 2023). "In summary, we can tentatively conclude that AE may improve cognitive impairment in T2DM mice by upregulating MALAT1 expression in serum-exosomes, competitively inhibiting miR-382-3p, and upregulating BDNF expression, thereby inhibiting hippocampal neuron apoptosis." (PMID 37740187, 2023). "LncRNA MALAT1 has also been reported to affect the CREB pathway, which contributes to cognitive deficits occurring during neurodegenerative diseases." (PMID 37714835, 2023). "In this study, we investigated the roles of MALAT1 and miR-382-3p in T2DM-related cognitive impairment and the therapeutic potential of AE in improving cognitive function in T2DM mice." (PMID 37740187, 2023). "AE may upregulate the expression of MALAT1 in serum-Exos to competitively inhibit miR-382-3p and upregulate BDNF expression, thus improving cognitive impairment in T2DM mice." (PMID 37740187, 2023). "In vivo experiments further confirmed that AE could increase the expression of MALAT1 in serum-Exos to competitively inhibit miR-382-3p and upregulate BDNF expression, thereby improving cognitive impairment in T2DM mice." (PMID 37740187, 2023). "However, the important role of MALAT1 and miRNAs in the occurrence of T2DM with OSA needs further study to find new treatment strategies to improve the health of patients with cognitive disorders." (PMID 32477065, 2020). "We also explored whether blocking the MALAT1/miR-224-5p/NLRP3 axis in activated microglia can inhibit nerve cell damage and ultimately reduce brain injury to alleviate cognitive impairment." (PMID 32477065, 2020).
endometrioid endometrial carcinoma (6 papers, 2018 to 2022). "In human endometrioid endometrial carcinoma cells, MALAT1 binds and sponges miR-200c, represses miR-200c expression and function, and is required for transforming growth factor β (TGFβ) function." (PMID 32174966, 2020). "MALAT1 binds and sponges miR-200c, and is required for TGFβ-induced endometrioid endometrial carcinoma cell EMT, migration, invasion." (PMID 32174966, 2020). "Data on the role of MALAT1 in endometrioid endometrial carcinoma is inconsistent." (PMID 32174966, 2020). "In human endometrioid endometrial carcinoma tissues, miR-200c levels are higher and MALAT1 levels are lower in tumor than non-tumor tissues." (PMID 32174966, 2020).
gastric tumor (6 papers, 2018 to 2024). "Unlike MALAT1 lncRNA expression, the fusion gene consisting of MALAT1 and glioma-associated oncogene 1 (GLI1; located at chromosome 12q13.3) is a diagnostic molecular marker for the rare gastric tumor plexiform fibromyxoma (PFM) and gastroblastoma." (PMID 37165307, 2023). "EZH2 protein level of gastric tumor tissue was reduced more than 50% by H2 exposure, which was enhanced by miR-124-3p and suppressed by lncRNA MALAT1." (PMID 33482814, 2021). "Consistent with our data, the lncRNAs H19, GAS5, TUG1, AP5M1, and MALAT1 were found to be overexpressed in TCGA database gastric tumors." (PMID 29719612, 2018). "Our method predicted CDKN2B-AS1, HOTAIR and MALAT1 as main correlated molecules with stomach neoplasms." (PMID 29671405, 2018). "Consistent with our results, we also found overexpression of lncRNAs such as H19, GAS5, TUG1, AP5M1 and MALAT1 and downregulation of LINCROR, POU3F3, HOTAIR, FALEC, NBAT1, and ZEB2-AS1 lncRNAs in TCGA gastric tumor datasets." (PMID 29719612, 2018). "The RNA-Seq results from the public database TCGA-TANRIC database showed that MALAT1, H19, and TUG1 were among the top twenty overexpressed lncRNAs in gastric tumors." (PMID 29719612, 2018).
hepatoblastoma (6 papers, 2013 to 2022). Hepatoblastoma (HB) is a malignant hepatic tumor and is the most common pediatric liver cancer. "Metastasis-associated lung adenocarcinoma transcript 1 (MALAT1) showed significant upregulation in neoplastic samples (HCC and highest in hepatoblastoma) compared to adjacent tumor and normal tissues." (PMID 33477833, 2021). "In an analysis of gene expression from HCC, hepatoblastomas, tissue adjacent to HCC tumors, and normal tissue, MALAT1 showed significant upregulation in neoplastic samples." (PMID 30159431, 2017).